IL6 (interleukin 6)
Diseases named in the same sentence as IL6 in open-access papers (continued):
Sharing a sentence is not in itself a finding about the gene and the disease.
Sepsis (continued). "There have also been contrasting results of IL-6 in diagnosing sepsis in the previous work, which may have been a result of different baseline patient characteristics." (PMID 27287669, 2016). "In contrast, CRP, PCT and IL-6 are available in most of the hospital laboratories, and their combination in an easily computable score could improve the accuracy of sepsis diagnosis." (PMID 27287669, 2016). "In the case of sepsis a significant increase of IL-6 (P = 0.0020), IL-8 (P = 0.0020), sIL-2R (P = 0.0156), and TNF-α (P = 0.0078) was observed in all pediatric patients (n = 8) for which an analysis of the cytokine levels was performed on the day of the occurrence of sepsis." (PMID 26315105, 2015). "To determine whether this functional ADAM10 SNP ultimately influences the expression of pro-inflammatory cytokines, we investigated the expression levels of IL-1ß and IL-6 in PBMCs from patients with severe sepsis." (PMID 25888255, 2015). "Serum IL-6 levels are known as a predictor of outcome in sepsis." (PMID 25844479, 2015). "IL-6 plays a decisive role in the trans-signaling pathogenesis of sepsis." (PMID 26315105, 2015). "The mechanisms by which Nrf2 controls the expression levels of IL-6 after DEPe exposure could be related to an activation of the nuclear factor NF-κB observed after a disruption of Nrf2 in a murine model of sepsis." (PMID 25710172, 2015). "However, the role of IL-6 as a marker to diagnose sepsis or predict outcomes remains uncertain, and a wide range of cutoff values had been used (from 12 to 2760 pg/ml)." (PMID 26502877, 2015). "Sepsis further increased IL-6 levels over the already elevated levels from the original injury." (PMID 26502877, 2015). "TNF-α and IL-6 are important pro-inflammatory cytokines in sepsis." (PMID 25873251, 2015). "On the other hand, IL-6 may be a more consistent predictor of sepsis and appears to correlate better with sepsis severity and mortality." (PMID 26081832, 2015). "Separate from this, a sepsis was characterized by significant increases of IL-6, IL-8 and sIL-2R." (PMID 26315105, 2015). "The increase of plasma IL-6 levels has been correlated with the severity of sepsis." (PMID 26507263, 2015). "Current evidence does not support a direct effect of IL-6-174 G/C polymorphism on the risk of sepsis." (PMID 25734339, 2015). "Increased concentrations of IL-6, found in ongoing sepsis of patients with poor prognosis, may promote the constitutive IDO activation leading to maintenance of a life-threatening immunosuppressive phase in sepsis." (PMID 26881062, 2015). "Sepsis was the systemic inflammatory responses to infections, and the circulating macrophages played an important role during these responses through the release of inflammatory cytokines, such as IL-6 and TNF-α." (PMID 25625512, 2015). "Burn sepsis induced profoundly elevated levels of IL-1 β, IL-6, TNF-α, and MCP-1 in serum." (PMID 26550025, 2015). "Historically, severe systemic inflammation—that is, release of tumor necrosis factor (TNF), monocyte chemoattractant protein-1 (MCP-1), interleukin-6 (IL-6), and other inflammatory mediators—was thought to play the major role in sepsis-induced multiple organ dysfunction syndrome (MODS)." (PMID 25959381, 2015). "Interestingly, although mice models of septicemia only partially reproduce the human disease, a high level of IL-6 in the serum of patients predicts a poor outcome in human septicemia." (PMID 25742129, 2015). "This study is part of a larger study to evaluate the characteristics of sepsis patients and its purpose is to study the relationship between gender and mortality due to sepsis and to identify differences if any between the cytokine levels specifically IL-6, IL-10 and TNF alpha between the genders." (PMID 26649014, 2015).
Sepsis (continued). "Furthermore, compared to the inflammatory response typically related to exercise, severe inflammation (e.g., sepsis) has been associated with a distinctively different cascade of cytokines in the circulation (i.e., TNF-α, IL-1β and IL-6 in that order)." (PMID 26378783, 2015). "In doses ranging from 25 to 75 mg/kg body weight, CSL-111 was able to suppress production of pro-inflammatory cytokines TNF-α, IL-6, and IL-8, inhibit sepsis-induced hypotension, and markedly decrease the severity of clinical symptoms when administered prophylactically." (PMID 26557091, 2015). "Next, we also observed that MyD88-deficient mice had a reduction in IL-6 in the plasma 6 h after non-severe sepsis induction." (PMID 25084278, 2014). "Target gene expression was stable over time in both patient groups, with the exception of IL-6 mRNA expression changing significantly over time in patients with uncomplicated sepsis (p = 0.019, Skillings-Mack) and UPAR in severe sepsis/septic shock (p = 0.024, Skillings-Mack)." (PMID 25343379, 2014). "Interleukin-6 levels are elevated in various inflammatory conditions of the gut including Crohn's disease, ulcerative colitis, and necrotizing enterocolitis, and in systemic inflammatory conditions such as sepsis and burn injury." (PMID 24662742, 2014). "The protection of female hearts against the dysfunction associated with sepsis is (at least in part) attributable to cardiac activation of the Akt/eNOS survival pathway, decreased activation of NF-κB, and decreased expression of iNOS, TNF-α and IL-6." (PMID 24945834, 2014). "This characteristic limits, to a great extent, the role of IL-6 and IL-8 as clinically useful biomarkers for all stages of sepsis, although they may be useful early in the disease prior to treatment in neonates." (PMID 25614712, 2014). "Corroborating the reduced systemic IL-6 levels, we also observed a reduction in neutrophil accumulation into the lungs of MyD88-deficient mice 6 and 24 h after non-severe sepsis induced by CLP." (PMID 25084278, 2014). "In addition, MyD88-deficient mice also showed increased bacterial load in the peritoneal cavity and blood, as well as reduced IL-6 levels in the plasma 6 h after severe sepsis induction." (PMID 25084278, 2014). "Analyses of the specific triplet LBP, TLR and IL-6 showed LBP A + TLR B + IL-6 A and LBP B + TLR A + IL-6 A combinations (P = 0.006; P = 0.012, respectively) to be at high risk for sepsis development, but occurrence of the proposed variants was low (4.2 and 4.8% of patients)." (PMID 24383711, 2014). "IL-6 has been found to be the principal offender of morbidity and mortality in bacteremic sepsis." (PMID 25120287, 2014). "This is further supported by the lack of immunoproteasome activation in our reanalysis of muscle transcriptomes from non-inflammatory myopathies, patients with severe inflammatory syndroms like sepsis or conditions related to high IL-6 levels in the circulation." (PMID 25098831, 2014). "In part, this may reflect the timing of patient's enrollment, since in a previous work we found a dynamic modulation of ex-vivo induction of TNF-α and IL-6 in whole blood of septic patients related to the stages of sepsis." (PMID 24667684, 2014). "In addition, severely injured male trauma-patients had a higher incidence of sepsis, multiple organ dysfunction syndrome and greater elevations in plasma procalcitonin and IL-6 compared with the equivalent group of females." (PMID 24945834, 2014). "IL-6 is one of the most common inflammatory cytokines, and its circulating levels have been shown to be excellent predictors of the severity of acute respiratory distress syndrome of different aetiologies, such as sepsis and acute pancreatitis." (PMID 25214712, 2014). "Since eHSPA12B level at 1d, 3d and 5d after sepsis was correlated with IL-6, the dynamic changes of eHSPA12B might be correlated with the changes of disease severity." (PMID 24977412, 2014).
Sepsis (continued). "Plasma IL-6 was significantly increased in the control group by 8 hours of sepsis (from 1.04 (0.86; 1.26) to 3.57 (2.96; 4.30) ng/mL) (P <0.001) and remained elevated at a similar level until 24 hours of sepsis." (PMID 25413250, 2014). "In this study, we did not detect different levels of circulating IL-6 or neutrophil accumulation in the lungs during sepsis in Nod1-, Nod2-, Nod1/Nod2- and Rip2-deficient mice compared to WT septic mice." (PMID 25084278, 2014). "At T0, serum concentrations of Resistin, NGAL, IL-6, IL-10 and IL-8 were significantly higher in patients with severe sepsis/septic shock compared to patients with uncomplicated sepsis (p = 4.5×10−5, p = 2.5×10−4, p = 0.002, p = 0.018 and p = 9.0×10−4 respectively, Mann Whitney)." (PMID 25343379, 2014). "IL-6 and IL-10 are important proinflammatory and anti-inflammatory cytokines during sepsis course." (PMID 24672147, 2014). "Hence, the caspase-1 function in sepsis was independentof processing and releasing IL-1β and IL-18, in spite of having reducedlevels of serum IL-1β, IL-18 and IL-6 incaspase-1−/− mice during sepsis." (PMID 25412304, 2014). "Genetic variation within the regulatory part of the IL-6 gene may affect the incidence and outcome of sepsis." (PMID 24383711, 2014). "Fifty-five patients with severe sepsis and 30 healthy donors were prospectively enrolled, and 90-day survival was compared between elderly (≥65 years) and adult (18–64 years) septic patients with serial measurement of serum interleukin (IL)-6." (PMID 24962182, 2014). "However, in patients with severe sepsis/septic shock, there were statistically significant changes over time in serum concentrations of Resistin, IL-6, IL-10, IL-8 and MCP-1 (p = 0.024, p = 3.5×10−6, p = 5.0×10−4, p = 0.002, p = 0.049, Skillings-Mack)." (PMID 25343379, 2014). "In this report, we measured the levels of tumor necrosis factor (TNF)-α, interleukin (IL)-6 and IL-8 in severely burned patients with sepsis after the initiation of continuous vein-vein hemodiafiltration (CVVHDF) to evaluate the clinical usefulness of CVVHDF on the removal of key mediators." (PMID 27602373, 2014). "The CS model had the greatest gene expression related to innate inflammatory pathways one day after sepsis with activation of pathways related to the role of pattern recognition receptors (PRRs), Il-1, Il-6, Nfkb, and Hmgb1 signaling, chemokine signing, TLR signaling, and the acute phase response." (PMID 24788351, 2014). "Other factors associated with increased risk include 15 % or more of bone marrow macrophages (odds ratio = 9.42; 95 % CI, 2.14–41.58, p < 0.01), sepsis (odds ratio = 7.77; 95 % CI, 1.48–40.9, p < 0.05), and high serum IL-6 levels (odds ratio = 1.00; 95 % CI, 1.00–1.0001, p < 0.05)." (PMID 24852692, 2014). "Therefore, the present study delivered new evidence about both presepsin and IL-6 as powerful prognostic biomarkers of short- and long-term prognosis in patients with severe sepsis and septic shock." (PMID 25190134, 2014). "As sepsis in patients was associated with elevated levels of TNF-α and interleukins (IL)-1, as well as IL-6 in cerebrospinal fluid, the pathophysiological mechanisms of SAE may be the result of a cascade of neuroinflammatory processes as followed." (PMID 25722876, 2014). "Many of the canonical pro-inflammatory pathways were activated in response to CLP-induced sepsis, including cytokine signaling (IL-10, IL-8 and IL-6), the NF-κB pathway, the pattern recognition pathway (Toll-like receptors), and the acute phase response pathway." (PMID 24732911, 2014). "IL-6 and IL-10 are important proinflammatory and anti-inflammatory cytokines in sepsis." (PMID 24672147, 2014). "As expected, for all sepsis patients on days 1 to 2 of illness, plasma levels of proinflammatory cytokines, IL-6 and IL-8, were significantly elevated compared with healthy controls (82 (21 to 396) pg/ml versus < 6 pg/ml and 50 (19 to 92) pg/ml versus < 15 pg/ml, respectively)." (PMID 25005517, 2014).
Sepsis (continued). "It seems that measurement of serum IL-6, 8, and 10 in newborns in whom there is a suspicion of sepsis, using the cut-off values reported in this study may predict neonatal sepsis and prevent overt hospitalization and antibiotics prescription." (PMID 24570828, 2013). "Among cytokines, circulating level of IL-6 has the best correlation with HRV indices in sepsis." (PMID 24340009, 2013). "Antibody to block IL-6 improved further survival of mice in a bacterium-derived sepsis model." (PMID 23431240, 2013). "A minimum of 2.0 g/kg body weight of immunoglobulins has been reported to be necessary in order to sufficiently neutralize the rise of IL-6 levels due to sepsis, which would be difficult to achieve in Japan given the reduced anti-cytokine effects from the lower immunoglobulin dosages." (PMID 25705399, 2013). "However, the finding of decreased circulating IL-6 concentrations in obese patients with sepsis is consistent with the observation of improved survival outcome." (PMID 23786836, 2013). "In patients, increased serum IL-6 predicts AKI in both ischemic AKI as well as sepsis-induced AKI." (PMID 24265742, 2013). "IL-6 levels were increased in the GdCl3 treated WT mice following induction of sepsis." (PMID 23076073, 2013). "AKI also leads to coagulation abnormalities and increased incidence of sepsis with multi-organ failure as well as to upregulation of cytokines (interleukin-1, interleukin-6, tumor necrosis factor-α) and/or immune-mediated major organ dysfunction (i.e. heart, lungs, and brain)." (PMID 23394360, 2013). "Levels of TNF-α and IL-6 were increased already at 6 h after sepsis induction in both genotypes." (PMID 23397596, 2013). "In patients with severe sepsis there was a significant association between sequential organ failure assessment (SOFA) scores and serum IL6 protein levels at ICU admission and 7 days after admission (admission P < 0.001, Spearman ρ = 0.796, n = 49; day 7 P < 0.001, Spearman ρ = 0.812, n = 30)." (PMID 23935244, 2013). "In the 1990s, sepsis was believed to be associated with an exacerbated release of mainly proinflammatory cytokines, such as tumor necrosis factor (TNF)-α, interleukin (IL)-1, IL-6, IL-12, interferon (IFN)-γ, and macrophage migration inhibitory factor (MIF)." (PMID 23853427, 2013). "Since high iNOS expression/protein and •NO activity in the sepsis literature are associated with high TNF-α, IL-6, and ensuing toxicity, we evaluated how HOCbl might impact upon systemic levels of TNF-α and IL-6 triggered by LPS." (PMID 23781123, 2013). "Circulating IL-6 levels seem to be correlated with the severity of sepsis." (PMID 23398965, 2013). "IL1β, IL-6, and TNFα are believed to play a central role in sepsis-mediated myocardial depression." (PMID 23691359, 2013). "Proinflammatory cytokines of sepsis (tumor necrosis factor A, interleukin 6, and interleukin 1b) have been shown to directly and negatively affect the survival of red blood cells in the circulation, promote deformability of the red blood cell membrane, and suppress erythrocyte maturation." (PMID 24216220, 2013). "Treg, IL-6, and IL-10 were higher in patients with septic shock than in patients with sepsis." (PMID 24249974, 2013). "No significant changes in proportions of IL-6+ cells were detected in any of the investigated cell subsets at this time-point, indicating that splenomegaly in severe sepsis survivors is associated with expansion of the TNF-producing Ly-6Chigh monocytes." (PMID 23808943, 2013). "Thus, like the IP endotoxin model, urine NGAL and IL-6 seem to be more related to the course of sepsis than to the course of renal function during sepsis." (PMID 24265742, 2013). "Human interleukin-6 (IL6) is a cytokine with pleiotropic functions that is involved in a broad range of biological activities and was found to be associated with a vast number of severe inflammatory diseases, sepsis and rheumatoid arthritis." (PMID 23372793, 2013).
Sepsis (continued). "Since elevation of IL-6 level in serum is observed at an early phase of sepsis, blockade of P2Y11 receptor might be effective for suppression of IL-6 over-production in the early phase of sepsis." (PMID 23577075, 2013). "Are IL-6 levels a reflection of timing of progression of sepsis?" (PMID 23251827, 2012). "Furthermore, studies have shown that levels of TNF-α, IL-1β, and IL-6 are markedly increased in patients with established sepsis." (PMID 22655058, 2012). "Importantly, anti-C5L2 antibody-treated mice showed increased serum IL-6 level during CLP-induced sepsis." (PMID 23233853, 2012). "Moreover, positive relationships between Ang2 and inflammatory cytokines, such as tumor-necrosis factor (TNF)-alpha and interleukin (IL)-6 are observed in severe sepsis." (PMID 23021336, 2012). "Plasminogen activator inhibitor-1, interleukin (IL)-1, IL-6, IL-8, and IL-10, and tumor-necrosis-factor-alpha mediate insulin resistance and are elevated in sepsis, while retinol-binding protein-4 concentrations are significantly reduced in sepsis." (PMID 22272381, 2012). "Similarly, early IL-6 results were good independent predictors of sepsis occurrence (adjusted OR 10.9, 95%CI 3.0; 39.4, p = .0002)." (PMID 22431998, 2012). "Based on our daily clinical experience in critical care of septic patients, we hypothesize that a correlation exists between the blood IL-6 level and hyperglycemia in sepsis." (PMID 22494810, 2012). "We may thus hypothesize that, after severe trauma, patients who do not restore their mHLA-DR expression and subsequently develop sepsis are those who presented the highest IL-6 values at days 1–2." (PMID 22431998, 2012). "In this preliminary study, the association between a lack of mHLA-DR recovery and IL-6 concentration at days 1–2 can result in a performance test to predict sepsis." (PMID 22431998, 2012). "Furthermore, TNFα and IL-6 are considered biomarkers of sepsis, and in this study their levels were reduced locally by MAT.Ang-1 during endotoxemia." (PMID 23036162, 2012). "Also, patients with clinical evidences of sepsis had a higher serum level of PCT and IL-6 within 12–24 hours after admission compared to the patients with uncertain sepsis." (PMID 22708043, 2012). "Nevertheless, IL-6 has pointed out as an important cytokine in sepsis with pro- and anti-inflammatory effects, regardless of whether it is a disease biomarker or contributes to severity of sepsis." (PMID 23137350, 2012). "Blood levels of TNF and IL-6 are high in most patients with severe sepsis." (PMID 22664467, 2012). "Importantly, neutrophil depletion resulted in a more than 50% decrease of IL-6 level, suggesting that neutrophils are the major contributor of C5a-regulated IL-6 production during sepsis." (PMID 23233853, 2012). "Plasma concentrations of PSP/reg (343.5 vs. 73.5 ng/ml, P < 0.001), PCT (39.3 vs. 12.0 ng/ml, P < 0.001), IL-8 (682 vs. 184 ng/ml, P < 0.001) and IL-6 (1955 vs. 544 pg/ml, P < 0.01) were significantly higher in patients with septic shock than with severe sepsis." (PMID 22748193, 2012). "For example, HA-1A may improve outcomes in patients with gram-negative infections and anti-TNF-α therapies may effectively treat patients with elevated IL-6 levels despite these individual therapies' inability to treat all-comers with sepsis." (PMID 23251827, 2012). "Plasma IL-6 level is also a marker for predicting infection and survival in patients with sepsis." (PMID 21939530, 2011). "IL-6 has been detected as early marker for postoperative sepsis." (PMID 22078633, 2011). "IL-6 is an important pro-inflammatory cytokine that is upregulated during sepsis." (PMID 21931850, 2011). "Moreover, PD-L1 blockade significantly improved survival, prevented sepsis-induced depletion of lymphocytes, increased tumor necrosis factor-alpha and IL-6 productions, decreased IL-10 production, and enhanced bacterial clearance in mice after CLP." (PMID 21418617, 2011).